RN7SL182P (RNA, 7SL, cytoplasmic 182, pseudogene)
Gene: Miscellaneous RNA gene on chromosome 3 (49,083,233 to 49,083,532, forward strand). Ensembl gene ENSG00000241461.
Homologues: Orthologues: chimpanzee Metazoa_SRP (99% identical), macaque Metazoa_SRP (90% identical). Paralogues in human: RN7SL1 (83% identical), RN7SL2 (82% identical), RN7SL3 (81% identical), RN7SL296P (79% identical), RN7SL357P (79% identical), RN7SL797P (79% identical), RN7SL664P (79% identical), RN7SL113P (78% identical), RN7SL126P (78% identical), RN7SL230P (78% identical), RN7SL145P (78% identical), RN7SL301P (78% identical), and 701 more.